MYC (MYC proto-oncogene, bHLH transcription factor)
Diseases named in the same sentence as MYC in open-access papers (continued):
Sharing a sentence is not in itself a finding about the gene and the disease.
breast cancer (continued). "We and others have recently demonstrated that the anticancer metabolic activity of metformin toward unsorted breast cancer cells is partially due to a mir-33a-dependent modulation of c-MYC levels." (PMID 24980829, 2014). "In the DMBA-induced rat mammary tumor model, MYC protein levels were higher in those tumors that acquired TAM resistance during treatment when compared with either TAM sensitive, de novo resistant, or untreated tumors." (PMID 25339305, 2014). "c-MYC has been reported as an estrogen-responsive gene and is a positive regulator of estrogen-stimulated breast cancer cell growth." (PMID 24735615, 2014). "Additional in silico analyses of whole genome ChIP sequencing (ChIP-Seq) data using the UCSC Genome Browser showed that RNA polymerase II and the c-MYC proto-oncogene are bound to the conserved region preceding the AKT1m exon in MCF7 breast cancer cells." (PMID 24628780, 2014). "MYC is a target of estrogen signaling in breast cancer cells that can control diverse aspects of cancer cell survival including cellular metabolic reprogramming." (PMID 25339305, 2014). "For instance, MYC/MYCN regulates the expression of miR-9 in breast cancer, and DNA methylation influences miR-9 expression in colorectal cancer." (PMID 24969351, 2014). "Our findings show that antiestrogen resistant breast cancer cells express higher levels of MYC protein compared with sensitive cells, and elevated MYC levels correlate with increased sensitivity to deprivation of glutamine and glucose." (PMID 25339305, 2014). "Antiestrogen resistant breast cancer cells with higher MYC activation showed increased sensitivity to small molecule inhibitors of glutaminolysis and glycolysis, but did not re-sensitize these cells to antiestrogens." (PMID 25339305, 2014). "These chromosomes contain genes that are commonly involved in the invasion, metastasis and pathogenesis of breast cancer, including c-MYC on 8q24; HRAS, CD151, CTSD on 11p15; CCND1 on 11q13; and TOP2A on 17q21." (PMID 24456987, 2014). "MYC activation in endocrine resistant breast cancer cells increased their dependency on glutamine and glucose." (PMID 25339305, 2014). "For example, MYC is overexpressed in several tumors; however, MYC is surprisingly involved in the repression of integrins, which are required for breast cancer cell invasion and motility." (PMID 24576043, 2014). "Known breast cancer oncogenes such as MYC (8q) and ERRB2 (17q), while among the common regions of amplifications, were not among the highly expressed genes in our samples." (PMID 24489661, 2014). "ER+ human breast cancer cell lines (LCC1, LCC1, LY2 and LCC9) and rat mammary tumors were used to confirm upregulation of MYC in endocrine resistance." (PMID 25339305, 2014). "We describe how MYC upregulation in ER + antiestrogen resistant breast cancer cells increases dependency on glucose and glutamine but enables cell survival in glucose-deprived conditions by increasing dependency on glutamine." (PMID 25339305, 2014). "In our endocrine resistant breast cancer cell models, MYC inhibition increased both JNK activation and LC3II levels, with an associated increased inhibition of cell growth in glutamine-only conditions." (PMID 25339305, 2014). "The known role of estrogen-induced MYC oncogene in breast cancer confirms a biological relevant regions-to-gene association." (PMID 25426335, 2014). "The results further suggest that aberrant c-MYC expression, which is frequently observed in human breast cancers, can contribute to the estrogenic effect by alteration of miR-26a and miR-26b expression." (PMID 24735615, 2014). "USP28 is a key regulator of the DNA damage checkpoint, high expression levels of USP28 are found in colon and breast carcinomas, and stabilization of MYC by USP28 is essential for tumour-cell proliferation." (PMID 24997798, 2014).
breast cancer (continued). "GE treatment led to increased expression of tumor suppressor genes, p16 and p21, whereas it decreased expression of tumor promoting genes, BMI1 and c-MYC, in both precancerous SH and breast cancer SHR cells at the mRNA." (PMID 23342141, 2013). "In five different breast cancer cell lines, the MYC and E2F reporter plasmids were transfected and assayed for the inherent un-induced transcriptional activity." (PMID 24147022, 2013). "MYC expression in breast cancers was surprisingly half that of normal tissue (p<0.001); in glioblastoma it was higher by a factor of 3.5 (p<0.001)." (PMID 23393560, 2013). "c-MYC protein was high in most TN breast cancer cell lines, including MDA-MB231 and MDA-MB468 as were levels of cyclin D1 in several TN breast cancer cell lines, including HCC38 and HCC1937." (PMID 24143235, 2013). "Wolfer and Ramaswamy (2011) investigated the role of MYC in breast cancer metastasis using a signaling pathway that includes let-7, miR-9, E-Cadherin, and EMT." (PMID 23365639, 2013). "It is known that amplifications of CCND1 and MYC frequently occur together in breast cancer; accordingly, we observed its down-regulation coupled with MYC down-regulation (logFC −1.2)." (PMID 23405235, 2013). "Knockdown of ATAD2 and MYC in seven endometrial and 21 breast cancer cell lines demonstrated that cell lines that were dependent on MYC also depended upon ATAD2." (PMID 23393560, 2013). "By integrative functional genomics investigation, we identified the involvement of EGFR, RAS, PI3K / AKT, MYC, E2F signaling in the regulation of these selected 1q genes in breast tumors and breast cancer cell lines." (PMID 24147022, 2013). "MYC expression correlated less strongly with 8q24 amplification in all three cancer types (R2 = 0.12, 0.07, and 0.10 for breast cancers, glioblastomas, and ovarian cancers respectively; p<0.001 in all cases)." (PMID 23393560, 2013). "To functionally confirm the relation between Trichostatin-A and MYC dependency, we tested all endometrial cancer and breast cancer cell lines for growth inhibition by Trichostatin-A and compared the results to MYC knockdown." (PMID 23393560, 2013). "Multiple mechanisms are involved in MYC deregulation in breast cancer, including gene amplification, transcriptional regulation, and mRNA and protein stabilization, which correlate with loss of tumor suppressors and activation of oncogenic pathways." (PMID 23874497, 2013). "In conclusion, our data suggest that SCFFBXO28 plays an important role in transmitting CDK activity to MYC function during the cell cycle, emphasizing the CDK-FBXO28-MYC axis as a potential molecular drug target in MYC-driven cancers, including breast cancer." (PMID 23776131, 2013). "We also find that endometrial and breast cancer cell lines that are dependent upon MYC expression also depend upon expression of ATAD2." (PMID 23393560, 2013). "In this context, we report that the c-MYC gene repressor MBP-1 negatively regulates ERBB2 gene transcription in SKBr3 breast cancer cells by targeting regulatory sequences in the promoter region." (PMID 23421821, 2013). "A higher proportion of breast cancers over-express MYC at the protein or mRNA level than exhibit MYC amplification." (PMID 23145106, 2012). "While RAD21 binding was consistent at some locations near MYC in all three breast cancer cell lines examined, there were differences at particular regulatory elements." (PMID 23145106, 2012). "Our work has potential clinical implications for the treatment of breast cancer and other MYC-driven cancers." (PMID 23145106, 2012). "Amplification was observed over cancer genes previously implicated in breast cancer development including ERBB2, CCND1, MYC, MDM2, ZNF217, and ZNF703 and a homozygous deletion involving MAP2K4 was identified." (PMID 22608084, 2012). "We found that cohesin was indeed necessary to maintain MYC transcript levels in three human breast cancer cell lines." (PMID 23145106, 2012).
breast cancer (continued). "Subsequently, we showed that ING4 suppressed T47D breast cancer cell growth in soft agar and MYC-initiated mammary hyperplasia in a mouse model, providing evidence for the ING4 tumor suppressor function in breast cancer." (PMID 23056468, 2012). "Amplification of MYC/PVT1 has been shown to contribute to the pathogenesis of ovarian and breast cancer, and is part of the chromosome 8q24 prostate cancer risk locus." (PMID 22661320, 2012). "MYC expression is constitutively higher in ER-negative breast tumors and hormone-independent breast cancer cell lines." (PMID 23145106, 2012). "High levels of MYC have been observed in breast cancer cases, both at the mRNA (22–35%) and protein (41–45%) level." (PMID 23145106, 2012). "Other genes, like epidermal growth factor receptor (EGFR), Fibroblast growth factor receptor 1 (FGFR1), topoisomerase IIa (TOP2A) and MYC are also involved in female breast cancer and have prognostic and therapeutic implications." (PMID 22527098, 2012). "Similar results were observed for phosphoglycerate dehyrogenease in breast cancer and melanoma versus MYC-induced lymphomagenesis." (PMID 23234303, 2012). "Another study showed that while lactate dehydrogenase A is important for breast carcinoma, neuroblastoma, and B-cell tumor cells, it is dispensable for MYC-induced lymphomagenesis." (PMID 23234303, 2012). "The most significant ones include TFF1, CCND1, IGFBP4, C3, ADORA1, GREB1, and MYC, which have been shown by candidate gene analysis to be estrogen regulated genes in breast cancer cell lines." (PMID 21878096, 2011). "SNP marker rs6983267 has been shown to exhibit long-range physical interaction with the proto-oncogene c-MYC (about 335 kb downstream) in colorectal, prostate, and breast cancer, providing a potential mechanism for the source of this association." (PMID 22142333, 2011). "This suggests that MYC gain is evolutionarily conserved in mammary tumor development from mouse to man." (PMID 20735817, 2010). "First, using univariate Cox-proportional hazards regression models we found that E2F3, MYC and RAS overactivation were associated with poor prognosis in ER+ breast cancer (P < 0.01)." (PMID 21050467, 2010). "We find that amplification of the MYC locus and the loss of the RB/INTS6 locus is evolutionarily conserved in mouse and human mammary tumor development, and that AURKA amplification is conserved in mouse and human BRCA2-mutated tumors." (PMID 20735817, 2010). "Coamplification of MYC and PVT1 seem to correlate with rapidly growing and progressive breast cancer and has been associated with poor outcome in postmenopausal or ERBB2-positive BC patients." (PMID 20932292, 2010). "We found that the basal subgroup of ER− breast cancer showed a strong MYC transcriptional response that reproduced the indirect estrogen response seen in estrogen receptor positive (ER+) breast cancer cells." (PMID 19270750, 2009). "We used a cell model of estrogen and MYC action to define the interaction between estrogen and MYC transcriptional activity in breast cancer." (PMID 19270750, 2009). "We show that enhanced transcriptional activity of MYC within the basal subgroup of ER− breast cancer mimics aspects of the transcriptional response to estrogen seen in ER+ cancers." (PMID 19270750, 2009). "A wide range of MYC transcript levels by RT-PCR has been detected in both ER+ and ER− breast cancers." (PMID 19270750, 2009). "Metastasis was not described in the earliest report on oncogene transgenic mice utilizing c-MYC for induction of breast carcinoma and pancreatic carcinoma." (PMID 19551151, 2009). "HSPC111 mRNA and protein were over-expressed in breast cancer cell lines and primary breast carcinomas, and this was positively correlated with MYC mRNA levels." (PMID 18373870, 2008).
breast cancer (continued). "Comparative analysis of HSPC111 and MYC mRNA expression revealed a weak positive correlation in this breast cancer cohort (r2 = 0.19, indicating that MYC contributed only about 20% of the variance in HSPC111 levels)." (PMID 18373870, 2008). "HSPC111 expression was also analyzed in relation to MYC expression and outcome in primary breast carcinomas and published gene expression datasets." (PMID 18373870, 2008). "We extended this study to examine the relationship between HSPC111 and MYC mRNA expression in a cohort of 105 primary breast carcinomas." (PMID 18373870, 2008). "Chromosomal amplifications have been described in breast cancer for several genes, including MYC at 8q24 and ERBB2 at 17q11.2." (PMID 16168117, 2005). "Likewise, in SK‐BR‐3 (HER + ) breast cancer cells, which display high levels of MYC, dasatinib showed synergy with both sirolimus and LY‐2940002." (PMID 41025936, 2025). "Our breast cancer findings suggest that c-MYC targeting represents a novel therapeutic axis distinct from BMP5/PTEN pathways, potentially offering unique advantages in hormone receptor-positive breast cancers where c-MYC dysregulation drives proliferative signaling." (PMID 40711670, 2025). "In addition, MYC has been reported to regulate the expression of several lncRNAs including MEG3 in breast cancer cells, with MYC overexpression enhancing MEG3 level and inhibition of MYC decreasing MEG3 expression." (PMID 40548301, 2025). "Our findings suggest miR-32-5p may act as an oncogenic contributor in breast cancer, potentially through c-MYC modulation." (PMID 40711670, 2025). "MYC amplification is frequent in breast cancers that have inactive BRCA1." (PMID 39885374, 2025). "Collectively, our findings reveal a novel mechanism by which lysine acetylation regulates AURKB stability, highlight the significance of the MOF-AURKB-c-MYC axis in breast cancer progression, and suggest potential therapeutic strategies targeting this pathway in clinical settings." (PMID 40710353, 2025). "The observed connection between miR-32-5p and c-MYC expression indicates that miR-32-5p levels may function as a biological indicator for c-MYC activity in breast cancers." (PMID 40711670, 2025). "Indeed, DDR1i caused differential expression in several direct RUNX1 target genes including DUT, an essential nucleotide metabolism enzyme seen upregulated across breast cancers, and MYC, along with ANP32B, PLEC, CEBPD, ID1, and STAT3." (PMID 40614729, 2025). "While we did not directly assess its impact on circulating FFA levels in our model, we found CL316243 to increase tumorigenesis and note that lipolysis-inducing agents could feed tumorigenesis in MYC-driven breast cancers with low GJB3." (PMID 40835606, 2025). "To elucidate the molecular mechanism by which MOF-mediated acetylation of AURKB at K215 promotes breast cancer cell proliferation, we first examined the expression levels of key oncogenic proteins, particularly c-MYC, following AURKB knockdown in MCF-7 and MDA-MB-231 cells." (PMID 40710353, 2025). "Interestingly we found a direct correlation when comparing circPVT1 and c-MYC expression levels in breast cancer TGCA database and MCF-10 A#circPVT1 expressing clones." (PMID 40114244, 2025). "The significant reduction in cell viability and increase in apoptosis following miR-32-5p inhibition, likely mediated through c-MYC downregulation, suggests a plausible pathway that may be targeted for therapeutic intervention in breast cancer." (PMID 40711670, 2025). "This study is the first to mechanistically link miR-32-5p to c-MYC suppression in breast cancer." (PMID 40711670, 2025).
breast cancer (continued). "MYC commonly drives TNBC which is more aggressive than other breast cancer subtypes." (PMID 40731028, 2025). "Similarly, CircACTN4 upregulates MYC transcription, enhances CDK4 and CCND2 expression, and drives breast cancer development and metastasis through MYC activation." (PMID 40804731, 2025). "In light of the regulatory influence of MYC on ASS1, targeting MYC and inhibiting arginine uptake may offer greater therapeutic benefits for breast cancer patients." (PMID 40732268, 2025). "In breast cancer (BC), miR-561-3p has been shown to downregulate PD-L1 expression by repressing certain oncogenes associated with breast cancer such as ZEB1, HIF1A and MYC." (PMID 39941003, 2025). "Indeed, MYC is the most frequently amplified gene in breast cancer, although other mechanisms are also likely to contribute to its increased expression." (PMID 39875774, 2025). "In addition, it has been shown that in breast cancer driven by cMYC amplification, combination of MYC plus mTOR inhibitors (AZD8055) synergized to suppress tumor growth in vivo." (PMID 40075567, 2025). "Furthermore, stiff ECMs lead to integrin β1-dependent β-catenin activation, which triggers MYC expression in breast cancer cells." (PMID 40124511, 2025). "Consequently, this downregulation suppresses expression of the downstream oncogene c-MYC, ultimately attenuating the malignant proliferation of breast cancer cells." (PMID 40710353, 2025). "We previously reported that circACTN4 could bind with FUBP1 to promote tumorigenesis and the development of breast cancer (BC) by increasing the expression of MYC." (PMID 40612865, 2025). "Interestingly, mice expressing a T58A mutant of c‐MYC in their mammary glands exhibited mammary carcinoma, elevated genomic instability, and suppressed apoptosis." (PMID 40227962, 2025). "Also inhibiting CDK1 has been reported to induce apoptosis selectively in MYC-dependent breast cancer cells." (PMID 38246945, 2024). "This is particularly relevant in ER+ breast cancers as MYC is a key factor responsible for driving the effects of estrogens on cell cycle progression and has been shown to be required for E2 dependent proliferation of ER+ breast cancer cells." (PMID 38965558, 2024). "In breast cancer, the expression and significative amplification of MYC are finely correlated with maintained tumor progression, and its transcriptional machinery is linked to aggressive cancer phenotypes with powerful abilities to invade local and distant tissues." (PMID 38204280, 2024). "Activation of MYC and IL-6 has been widely reported in breast cancer progression." (PMID 38654350, 2024). "Additionally, FUBP1 can be competitively bound by circACTN4, resulting in reduced FIR-binding and subsequently triggering the activation of c-MYC transcription, which leads to the progression of breast cancer." (PMID 38443680, 2024). "Moreover, a TCGA database analysis showed that KLHL42 mRNA was amplified in pancancer contexts, especially in breast cancer, bladder cancer and prostate cancer, and was significantly correlated with MYC protein levels in bladder cancer." (PMID 38424044, 2024). "Based on these observations, we postulated that the cellular response to MYC-induced DNA damage may promote cGAS activation and tumour suppression in this transgenic breast cancer model." (PMID 38200309, 2024). "For the most part, data presented in this study are consistent with previous observations showing over-expression and amplification of MYC in breast cancers, with a notable correlation between MYBL1 and MYC amplification alterations in the TCGA 1015 patient sample TNBC dataset." (PMID 38473786, 2024).